IL10 (interleukin 10)
Diseases named in the same sentence as IL10 in open-access papers (continued):
Sharing a sentence is not in itself a finding about the gene and the disease.
renal fibrosis (continued). "Overexpression of IL-10 was previously noticed in kidneys of mice challenging development of renal fibrosis during chronic leptospirosis." (PMID 27219334, 2016). "In a unilateral ureteral obstruction model, IL-10 overexpression promoted HA synthesis and reduced renal fibrosis, which could be inhibited by HA synthesis inhibitor, 4-methylumbelliferone (4-MU)." (PMID 38802835, 2024). "IL-10 is a key mediator of anti-inflammatory pathways which can impact renal fibrosis." (PMID 39234562, 2024). "Previous studies have proved that M2 macrophages can mediate renal fibrosis by secreting anti-inflammatory cytokines IL-10 and TGF-β1, as well as vascular endothelial growth factor (VEGF) promoting angiogenesis, or the transition of monocyte/macrophage to myofibroblast." (PMID 37029114, 2023). "In conclusion, we have demonstrated that the depletion of macrophages by clodronate liposomes can partially attenuate renal fibrosis in I/R injury through IL-10 and TGF-β, which may be correlated with M1/M2 polarization." (PMID 36636989, 2023). "A host-guest complex formed by CD modified hyaluronic acid (HA-CD) and Ad modified hyaluronic acid (HA-Ad) was prepared to co-deliver anti-TGF-β and anti-inflammatory cytokine interleukin-10 (IL-10) to treat chronic kidney disease (CDK) for localized immunotherapy to avoid renal fibrosis." (PMID 33562215, 2021). "IL-10 has been shown to reduce renal fibrosis by reducing macrophage infiltration and apoptosis." (PMID 29255249, 2017). "Recently, the connection between IL-10 and renal fibrosis has been suggested." (PMID 26199463, 2015). "The involvement of other members of the IL-10 cytokine family like IL-24, IL-26, IL-28, and IL-29 in renal fibrosis is completely unknown." (PMID 26199463, 2015). "Thus, clodronate liposomes can alleviate renal fibrosis and tissue damage and reduce the inflammatory cytokines IL-10 and TGF-β, suggesting that clodronate liposomes alleviate renal fibrosis may because of M1/M2 polarization." (PMID 36636989, 2023). "For example, PMSCs could inhibit the inflammatory response by regulating CD4+ T cell and macrophage polarization, inhibiting the inflammatory factors IFN-γ and IL-17, and upregulating the anti-inflammatory factor TGF-β and IL-10 expression to attenuate renal fibrosis in rats." (PMID 35450295, 2022). "The administration of an AAV vector designed for expression of IL-10, which is an anti-inflammatory cytokine, was shown to over-express IL-10 in plasma and inhibit renal fibrosis by inhibiting infiltration of T lymphocytes and macrophages in a rat model of renal fibrosis." (PMID 30410705, 2017). "Macrophage conversion to the M2 anti-inflammatory phenotype and the subsequent release of inflammatory factors, such as IL-10 and TGF-β, play a crucial role in the advancement of renal fibrosis in DKD." (PMID 40092979, 2025). "M1 macrophages, prevalent in DN, initiate inflammation, tissue damage, and renal fibrosis via proinflammatory cytokines such as TNF-a, IL-6, IL-10, and monocyte chemoattractant protein 1 (MCP-1)." (PMID 41438111, 2025). "Our data demonstrated that CO decreased inflammation, oxidative stress and renal fibrosis, as evidenced by quantifying the expression of TNF-α, IL-10, CAT, SOD, α-SMA and TGF-β." (PMID 37447251, 2023). "We have previously demonstrated the effect of the local delivery of IL-10 via HA hydrogels in a bilateral ischemia-reperfusion murine model of AKI in decreasing systemic inflammation and renal fibrosis." (PMID 37443806, 2023). "Our results surprisingly reveal a pro-inflammatory role of IL-10 inducing immune cell recruitment into the obstructed kidney in neonatal mice with UUO without altering the course of renal fibrosis development following UUO." (PMID 38448513, 2024). "Therefore, our findings demonstrate that the role and mechanism of dexamethasone mediate the expression and secretion of TGF‐β and IL‐10 in MDSCs by promoting the expression of ILT4, thereby leading to renal fibrosis." (PMID 38676361, 2024).
renal fibrosis (continued). "From these findings we conclude that IL-10 does not play a major role in the development of renal fibrosis in neonatal kidneys with UUO." (PMID 38448513, 2024). "Similarly, we also previously demonstrated that the delivery of either anti-TGF-β or IL-10 within HA improved renal fibrosis in a murine model of CKD, while in combination their delivery worsened renal fibrosis." (PMID 37443806, 2023). "M2 macrophages secrete high amounts of IL-10 and TGF-β to suppress inflammation; therefore, the depletion of macrophages by clodronate liposomes may partially attenuate renal fibrosis because of M1/M2 polarization." (PMID 36636989, 2023). "We have also demonstrated that HA hydrogel treatment alone, even in the absence of IL-10, reduced markers of inflammation and renal fibrosis, and that HA hydrogel delivery under the kidney capsule does not impact tGFR." (PMID 37443806, 2023). "Besides, the levels of cytokines, including the net renal release of IFN-γ, TNF-α, IL-10, and MCP-1, as well as renal fibrosis, also responded to MSC therapy." (PMID 36302933, 2022). "In addition, macrophages can produce IL-10 and TGF-β after the phagocytosis of apoptotic cells, and these factors can induce the proliferation of myofibroblasts and promote the occurrence of renal fibrosis." (PMID 34112221, 2021). "In renal fibrosis, it was demonstrated in a mouse model that a lack of IL-10 aggravated kidney inflammation and fibrosis." (PMID 34830373, 2021). "The role of IL-10 has not been fully investigated in renal fibrosis in diabetic kidney disease so far." (PMID 33888696, 2021). "Our work suggests that basal levels of IL-10 do not represent a form of protection against renal fibrosis in the hypertensive animals." (PMID 31360120, 2019). "Therefore, we reasonably speculate that long‐term adoptive transfer of MDSCs and high‐dose dexamethasone treatment promote renal fibrosis through TGF‐β and IL‐10 secretion." (PMID 38676361, 2024). "Furthermore, the downregulation of Galectin-3 transcription has been associated with a reduction in inflammatory cell polarization and a decreased secretion of the profibrotic factors such as Arg-1, CD206, IL-10, and TGF-β, resulting in diminished renal fibrosis." (PMID 39407295, 2024). "Furthermore, ERS and IL-10 interact during the progression of renal fibrosis, though the mechanism involved has not been elucidated." (PMID 36142626, 2022). "Notably, long term changes such as renal fibrosis were not different between neonatal Il-10−/− and neonatal WT mice with UUO suggesting that IL-10 signaling is different in neonates and adults with UUO." (PMID 38448513, 2024). "In line with increased inflammation in the mice lacking IL-10 they found a more pronounced collagen I deposition and increased expression of fibronectin, α-SMA, fibroblast-specific protein-1, vimentin, and MMP-2 supporting the development of renal fibrosis." (PMID 26199463, 2015).
dermatitis (42 papers, 2011 to 2026). An inflammatory process affecting the skin. "We also found that the application of H4R antagonists reverses the inflammatory effect associated with the Th2/Tc2 profile, a mechanism that involves an immunosuppressive response, dependent, in part, on IL-10 production, leading to an improvement in the symptoms associated with dermatitis." (PMID 36275674, 2022). "The downregulation of the Th2-dominant skin inflammation by GMP administration may be associated with the increased expression of IL-10, a known regulatory cytokine." (PMID 28265582, 2017). "There is evidence in the literature that probiotic intake can modulate IL-10 and Treg cells in the blood of patients with dermatitis." (PMID 40431255, 2025). "Since IL-10 and IL-1rn are key anti-inflammatory cytokines that regulate tissue inflammation, an acute dermatitis model was employed." (PMID 39594490, 2024). "Accordingly, the populations of representative Breg subsets—IL-10-producing B cells and CD24hiCD38hi transitional B cells—do not always exhibit a consistent correlation with each other in various skin disorders." (PMID 38426103, 2024). "In summary, the collective evidence underscores the suppressive role of IL-10-producing regulatory B cells in mitigating cutaneous inflammation, corroborated by the dysfunctional behavior of Bregs in skin disorders." (PMID 38426103, 2024). "The presence of inflammatory cytokines, such as interleukin-6 (IL-6) and interleukin-10 (IL-10), which are both indicators of dermatitis, was also tested for." (PMID 38665149, 2023). "Oral propionate greatly and the HFD modestly increased the expression of IL-10 in imiquimod-induced dermatitis." (PMID 37762500, 2023). "Oral propionate reduced inflammatory infiltrates and epidermal Ki67+ cells and reduced mRNA levels of IL-17A, IL-17F, IL-17C, IL-22, IL-1β, IL-6, TNF-α, CXCL1, CCL20 and increased those of TGF-β1and IL-10 in imiquimod-indued dermatitis." (PMID 37762500, 2023). "Faslpr mice developed more severe renal disease and dermatitis compared with their IL-10–intact counterparts, indicating that a 50% reduction in global IL-10 gene dose exacerbates SLE." (PMID 35192551, 2022). "The researchers observed an increase in the severity of dermatitis with an increase in IL-2 and IL-17 expression levels and a decrease in the severity of dermatitis with a decrease in the expression of IL-4 and IL-10 expression levels." (PMID 35431950, 2022). "It is noteworthy that IL-10 plays a role in suppressing inflammatory reactions, including in skin disorders and downregulation of IL-10 occurs in active DD." (PMID 33007829, 2020). "In many inflammatory disease models, such as chronic enterocolitis, skin inflammation, endotoxin shock, and encephalomyelitis, IL-10 plays a central role in the inflammatory response." (PMID 31398908, 2019). "It has been established that IL-10 plays a role in suppressing inflammatory reactions, including those in certain skin disorders." (PMID 30072966, 2018). "In the atopy-like dermatitis mouse model, the expression of Th2 cytokines such as IL-4, IL-5, and IL-10 in the lymph nodes of TMA-treated mice was found to be elevated, and BVA largely abrogated TMA-induced production of Th2 cytokines." (PMID 26825274, 2016). "Although immunofluorescent staining was not performed in this study, our previous report demonstrated Foxp3/IL‐10 double‐positive cells by immunofluorescence in IMQ‐induced dermatitis treated with maxacalcitol, supporting the current immunohistochemical findings." (PMID 41137524, 2026). "Consequently, this result proves that A06, B03, and B05, identified as MsrB1 inhibitors, suppress the expression of IL-10 and IL-1rn and, thereby, promote skin inflammation." (PMID 39594490, 2024). "Oral propionate increased mRNA expression of TGF-β1 and IL-10 in imiquimod-induced dermatitis." (PMID 37762500, 2023).
dermatitis (continued). "Previous studies have shown that IL-6 was an important immunomodulatory signal essential for the repair of UV radiation damage to the skin through induction of IL-10 and for limiting dermatitis following irritant contact through deregulation of IL-22R expression." (PMID 33804336, 2021). "In addition, the decreased IL-10 mRNA expression levels were also detected in the IRF5 KO mice and thought to be associated with the exacerbation of skin inflammation." (PMID 32456211, 2020). "Interleukin 10 is expressed by lymphocytes and neutrophils and negatively regulates the expression of pro-inflammatory cytokines; thus, it plays a role in resolving skin inflammation." (PMID 30072966, 2018). "As IL-10 has demonstrated promise in a phase II trial for cutaneous disorders, therefore, our observation that IL-10 gene was drastically upregulated suggests that WCR may have antipsoriatic properties." (PMID 28900461, 2017). "Additionally, specific deletion of MyD88 in DCs prevented the development of dermatitis with decrease expression of the proinflammatory cytokines IL-6 and IL-12, and different B cell-stimulating cytokines, including IL-10 with hampered B cell proliferation in MRL.Faslpr mice." (PMID 31546763, 2019). "A significant positive correlation was observed between IL-10 and IFN-γ levels (r = 0.52, n = 62, p < 0.001), as well as between IL-10 and the viral load at the time of onset of skin disorders (r = 0.3, n = 62, p < 0.05) in this group of patients." (PMID 40572779, 2025). "A positive correlation between IL-10 and IFN-γ levels in patients with HIV-related skin disorders has been noted in studies involving infants with HIV." (PMID 40572779, 2025). "Both indoles decreased the induction of IL-17 but promoted IL-10 and FoxP3 expression in mice expressing AHR, attenuating skin inflammation." (PMID 34831399, 2021). "Administration of exogenous IL-10 reverted chronic skin inflammation induced by TLR2 ligands and IL-4 indicating a crucial role for sustained production of IL-10 in response to cutaneous exposure to microbes." (PMID 26217343, 2015). "Serum vitamin D and plasma IL-10 levels did not significantly differ between moderate and severe dermatitis patients." (PMID 40630332, 2025). "The HFD significantly increased mRNA expression of anti-inflammatory cytokine TGF-β1 in imiquimod-induced dermatitis, and appeared to augment that of another anti-inflammatory cytokine IL-10, though the difference between NDI and HFDI was not significant." (PMID 37762500, 2023). "Unlike in other immune-mediated skin disorders, it has been observed that in HS there is a high expression not only of pro-inflammatory cytokines but also of the anti-inflammatory mediator IL-10." (PMID 33182701, 2020). "In the case of a skin disorder, activated keratinocytes produce a neuropeptide to enhance IL-10 expression for creating negative feedback signals for modulating inflammatory responses in the skin." (PMID 32802141, 2020). "All mice with oxazolone-induced dermatitis had a dramatic increase in IL-1β, IL-4, IL-6, IL-10, TNF-α, IFN-γ, IL-16, IL-17C, IL-17E, IL-17F, IL-21, IL-22, and MIP-3a, whereas the concentrations of IL-12p70, IL-2, IL-17A, and IL-23 were lower in dermatitis mice." (PMID 37889696, 2023). "Importantly, mRNA levels of Foxp3, IL-10, and TGFβ were significantly decreased in TLR2 KO mice compared with WT mice, suggesting that downregulation of Tregs and impaired IL-10 production in TLR2 KO mice increased Th1 cytokine mRNA levels and exacerbated the imiquimod-induced skin inflammation." (PMID 33202847, 2020).
systemic inflammatory response syndrome (42 papers, 2005 to 2026). SIRS is a serious condition related to systemic inflammation, organ dysfunction, and organ failure. "In most acute inflammatory responses, IL-10 can mediate a compensatory anti-inflammatory response to alleviate systemic inflammatory response syndrome." (PMID 34681392, 2021). "There is a consensus as to a protective effect of IL-10 on the inflammatory action of TNF-α during systemic inflammatory response syndrome." (PMID 29357879, 2018). "Effects of CO administration on cytokine (TNF-alpha, IL-6, IL-1beta and IL-10) release were investigated in a porcine model in which a systemic inflammatory response syndrome was induced by endotoxin infusion." (PMID 18687112, 2008). "IL-10 reduces the release of TNF-α into the circulation which hinders the development of a systemic inflammatory response syndrome, and this correlates with an increase in survival." (PMID 18937852, 2008). "It is unlikely that the systemic inflammatory response syndrome response elicited by the extracorporal bypass has a major role because IL-6 and IL-10 production in the mediastinal cavity exceeded systemic production 1,000-fold and 10-fold, respectively." (PMID 16356228, 2005). "Such IL10 increases might reflect mechanisms in patients with systemic inflammatory response syndrome that counteract organ failure." (PMID 39355237, 2024). "Accordingly, an in silico analysis of published IFNγ and IL10 values in bacteremic and non-bacteremic patients with the Systemic Inflammatory Response Syndrome supported this association between the ratio and pathogen burden." (PMID 33767693, 2021). "Serum levels of IL-10 upon admission to hospital were higher in patients with severe CAP meeting systemic inflammatory response syndrome (SIRS) criteria and in those in need of intensive care unit admittance and mechanical ventilation compared to patients with non-severe CAP." (PMID 34589087, 2021). "Further it was noted that IL-10 encoding SNP genes were found responsible for exacerbating systemic inflammatory response syndrome (SIRS) score during CAP infection but not the TNF-α and IL-6 cytokines." (PMID 33634060, 2020). "In systemic inflammatory response syndrome (SIRS), anti-inflammatory cytokines (IL-10, IL-4, IL-13, and PGE2) balance pro-inflammatory cytokines, a process known as the “cytokine storm”, leading to excessive inflammation." (PMID 39337069, 2024). "This immune-mediated injury, accompanied by elevated concentrations of IL-1, IL-2, IL-10, and IFNγ, would lead to systemic inflammatory response syndrome (SIRS)." (PMID 35464491, 2022). "A study based on a mouse model of systemic inflammatory response syndrome (SIRS) induced by D-galactosamine (D-GAL) combined with CpG ODN showed that sTLR9+ neutrophil can produce both TNF-α and IL-10 in the inflammatory site." (PMID 37724102, 2023). "In addition, there was an inflammatory cytokine reduction (IL-6 and IL-10), therefore, the BAK had a protective effect from systemic inflammatory response syndrome (SIRS) and multi-organ failure." (PMID 33751266, 2021). "The CD49d+CD11b− N1 neutrophils isolated from SCIDbg mice with mild systemic inflammatory response syndrome (SIRS) secrete the cytokine IL-12 and chemokine CCL3, while CD49d−CD11b+ N2 neutrophils isolated from SCIDbg mice with severe SIRS mainly produce IL-10 and CCL2." (PMID 31727175, 2019). "On contrary, circulating IL-6 and IL-10 is assessed as prognostic markers of severity of the disease in the elderly, and these inflammatory indices categorize patients into systemic inflammatory response syndrome (SIRS) and non-SIRS groups." (PMID 24049644, 2012). "KICS, a more recently recognized condition, is characterized by systemic inflammatory response syndrome (SIRS) with high levels of HHV-8 viremia and elevated interleukins (IL-6 and IL-10)." (PMID 40407649, 2025).
systemic inflammatory response syndrome (continued). "Paradoxically, these same patients showed hypomethylation of the IL-10 gene, suggesting concurrent activation of anti-inflammatory pathways (TGF-β, IL-10, IL-13) as part of the CARS that follows systemic inflammatory response syndrome (SIRS)." (PMID 40868190, 2025). "Interestingly, there was no significant change in the secretion of IL-10, an anti-inflammatory cytokine that plays a critical role in dampening systemic inflammatory response syndrome, leading to survival in T. congolense-infected mice." (PMID 25875604, 2015).